CENPK (centromere protein K)
Diseases named in the same sentence as CENPK in open-access papers (continued):
Sharing a sentence is not in itself a finding about the gene and the disease.
glioma (3 papers, 2021). A benign or malignant brain and spinal cord tumor that arises from glial cells (astrocytes, oligodendrocytes, ependymal cells). "In glioma, CENPK was linked to TCGA subtypes and tumor grades." (PMID 34044826, 2021). "LINC01158 served a pro-proliferative and anti-apoptotic part in glioma by sponging miR-6734-3p to augment CENPK." (PMID 34044826, 2021). "More importantly, we testified that LINC01158 augmented CENPK expression in glioma cells through sponging miR-6734-3p." (PMID 34044826, 2021). "Collectively, our work supported the oncogenic role of LINC01158 in glioma via miR-6734-3p/CENPK signaling." (PMID 34044826, 2021). "In this study, CENPK was confirmed to be increased in glioma cells and gain-of-function assays demonstrated CENPK as a growth-accelerator in glioma." (PMID 34044826, 2021). "LINC01158 facilitated glioma cell malignant phenotypes through elevating CENPK via its sponging on miR-6734-3p, which is of value for therapeutic strategies in glioma." (PMID 34044826, 2021). "To further substantiate that LINC01158 aggravated malignancy in glioma through miR-6734-3p/CENPK signaling, we conducted a series of rescue assays." (PMID 34044826, 2021). "Then, a positive correlation between LINC01158 and CENPK expression in glioma was plotted from GEPIA database." (PMID 34044826, 2021). "Overexpression efficiency of CENPK was ensured in pcDNA3.1/CENPK-transfected glioma cells by qRT-PCR." (PMID 34044826, 2021). "Then, our study also identified Centromere protein K (CENPK) as the potential downstream of LINC01158 in glioma." (PMID 34044826, 2021). "Overall, LINC01158 sponged miR-6734-3p to augment CENPK expression in glioma." (PMID 34044826, 2021). "Moreover, qRT-PCR analyzed that decreased CENPK expression due to LINC01158 silencing was restored when miR-6734-3p was further inhibited in glioma cells." (PMID 34044826, 2021). "Collectively, overexpressed LINC01158 positively regulated CENPK in glioma." (PMID 34044826, 2021). "Besides, we discovered CENPK expression was elevated in glioma, and the positive regulation of LINC01158 on CENPK expression was confirmed in glioma." (PMID 34044826, 2021). "Besides, it was disclosed that overexpressing CENPK strengthened colony formation ability and cell viability, and enhanced proportion of EdU-positive cells in glioma, certifying CENPK as a growth-facilitator in glioma." (PMID 34044826, 2021). "Moreover, we also confirmed the elevation of CENPK at both mRNA and protein levels in glioma cell lines relative to NHA." (PMID 34044826, 2021). "Functional assays indicated LINC01158 and CENPK was pro-proliferative to glioma cells." (PMID 34044826, 2021). "Then, we tested whether CENPK was required in LINC01158-regulated glioma development." (PMID 34044826, 2021). "LINC01158 enhances CENPK by serving as sponge for miR-6734-3p to facilitate glioma development, proposing LINC01158 as a new player in glioma." (PMID 34044826, 2021). "In this study, we discovered that CENPK and LINC01158 were both increased in glioma cells and tissues, and positively correlated with each other." (PMID 34044826, 2021). "LINC01158 and CENPK were both overexpressed in glioma and a positive regulation of LINC01158 on CENPK was corroborated." (PMID 34044826, 2021). "qRT-PCR, western blot and GEPIA database were applied for reporting the expression of CENPK and LINC01158 in glioma and the correlation between LINC01158 and CENPK expression." (PMID 34044826, 2021). "With respect to glioma cell apoptosis, the outcomes of caspase-3 activity and TUNEL assays unveiled that cell apoptosis was enhanced because of LINC01158 repression, while the elevation of CENPK effectively attenuated the promoted trend." (PMID 34044826, 2021).
glioma (continued). "Two hundred and eighty targets were upregulated or downregulated in 14 cancer types, among which BAX, CENPK, DLL3, and NOTCH3 showed a consistent upregulation in multiple cancers and glioma, indicating that these genes may play a carcinogenic role in a variety of cancers." (PMID 34589481, 2021).
bladder cancer (2 papers, 2021 to 2022). "CENPK was reported to have a decisive influence on the correct kinetochore function and, mitotic progression, and is associated with cell cycle and mitotic spindle assembly in bladder cancer." (PMID 34382342, 2021).
gastric cancer (2 papers, 2021 to 2024). A primary or metastatic malignant neoplasm involving the stomach. "Therefore, we used the Pearson correlation coefficient in GEPIA to detect the correlation between CENPK and PTEN in TCGA gastric cancer samples." (PMID 34382342, 2021). "Nevertheless, the potential function of CENPK in gastric cancer (GC) remains unknown." (PMID 34382342, 2021).
lung adenocarcinoma (2 papers, 2021 to 2022). A carcinoma that arises from the lung and is characterized by the presence of malignant glandular epithelial cells. "We assessed the prognostic value of CENPK mRNA expression in patients with lung adenocarcinoma using Kaplan–Meier survival analysis." (PMID 33478508, 2021). "However, the relationship between the CENPK gene and the development of lung adenocarcinoma (LAC) is not well characterized in the contemporary literature." (PMID 33478508, 2021). "However, the role of CENPK in the progression of lung adenocarcinoma (LAC) is not well characterized." (PMID 33478508, 2021).
pancreatic cancer (2 papers, 2022 to 2024). "For example, ZC3H13 mediates m6A modification of CENPK mRNA to increase translation of PHF10 in a YTHDF1-dependent manner, which in turn inhibits pancreatic cancer." (PMID 38351022, 2024).
follicular thyroid adenoma (1 paper, 2021). A benign, encapsulated tumor, arising from the follicular cells of the thyroid gland. "CENPK mRNA expression was measured within PTC, FTC and FTA (follicular thyroid adenoma) specimens and explored the roles of CENPK in DTC carcinogenesis, proliferation, and migration both in vivo and in vitro." (PMID 33904381, 2021).
follicular thyroid cancer (1 paper, 2021). "The present work suggested that the expression of CENPK remarkably increased in follicular thyroid cancer and papillary thyroid cancer tissue samples at the mRNA level." (PMID 33904381, 2021).
lung carcinoma (1 paper, 2021). "In this study, we identified CENPK as a potential new gene for lung cancer based on bioinformatics analysis." (PMID 33478508, 2021). "Then, for evaluating the biological behavior and role of CENPK in lung cancer cells, we did a series of vitro experiments, such as immunohistochemistry analysis, Western blot analysis, CCK8 assay, transwell assay, flow cytometry, and wound healing assay." (PMID 33478508, 2021). "Additionally, cell function experiments verified the biological behavior of CENPK in lung cancer." (PMID 33478508, 2021).
non-small cell lung carcinoma (1 paper, 2022). A group of at least three distinct histological types of lung cancer, including non-small cell squamous cell carcinoma, adenocarcinoma, and large cell carcinoma. "About the signaling pathway involved in miR-211-5p, the miR-211-5p/CENPK axis in tongue squamous cell carcinoma and the miR-211-5pp/BRD4 axis in non-small cell lung cancer have been reported, but not about resistance mechanisms." (PMID 35311096, 2022).
ovarian tumors (1 paper, 2015). "To understand whether the CENPK expression level was associated with clinical outcomes of ovarian tumors, we first investigated CENPK expression in ovarian tissues." (PMID 26587348, 2015).
periodontitis (1 paper, 2024). An acute or chronic inflammatory process that affects the tissues that surround and support the teeth. "BST2, CENPU and CENPK are the potential undiscovered genes that are related to the regulation of periodontitis." (PMID 38919957, 2024). "Additionally, C1QA exhibited a correlation with inflammation in geneCards, which implied that CENPK, CENPU and BST2 could feasibly manifest as factors linked to periodontitis." (PMID 38919957, 2024). "The identified biomarkers C1QA, CENPK, CENPU, BST2 and LINC01133 provided valuable insight into periodontitis pathology." (PMID 38919957, 2024).
prostate carcinoma (1 paper, 2024). A carcinoma that arises from epithelial cells of the prostate gland. "While the CENPK Exon 8 skip event is relatively rare in patients with primary prostate cancer (1.3%), it is more prominent in those with mCRPC." (PMID 39404386, 2024). "However, prostate cancer patients exhibit increased exon-skipping events in the CENPK gene." (PMID 39404386, 2024).
triple-negative breast carcinoma (1 paper, 2021). An invasive breast carcinoma which is negative for expression of estrogen receptor (ER), progesterone receptor (PR), and human epidermal growth factor receptor 2 (HER2). "Overexpression of CENPK was associated with poor outcomes in patients with triple-negative breast cancer." (PMID 33478508, 2021).
cancer (14 papers, 2015 to 2024). A tumor composed of atypical neoplastic, often pleomorphic cells that invade other tissues. "An increasing body of evidence has implicated dysregulation or dysfunction of CENPK in cancer progression." (PMID 33478508, 2021). "Moreover, IHC staining of CENPK protein indicated a positive association with Ki67 protein levels and was positively correlated with cancer recurrence." (PMID 35418160, 2022). "As a less studied member of the centromere protein family, CENPK was associated with tumorigenesis, implying that CENPK might serve as a prognostic target for cancers." (PMID 34382342, 2021). "Meanwhile, CENPU and CENPK also existed in the core PPI network and were associated with cancer cell value-added and differentiation-related processes." (PMID 38919957, 2024). "In the last five years, the role of CENPK has been gradually discovered in cancers and become a research hotspot." (PMID 37938151, 2023). "CENPK expression was elevated in pan-cancer datasets compared to that in corresponding normal tissues based on TCGA." (PMID 35418160, 2022). "Previous studies have indicated that centromere protein K (CENPK) is upregulated in several cancers and related to tumorigenesis." (PMID 34382342, 2021). "To determine the expression of CENPK in other cancers, we performed a comprehensive analysis of 33 types of tumors from TCGA." (PMID 33478508, 2021). "Recently, CENPK expression is reported to increase in several cancer tissues in vivo and in vitro, which is related to pathological stage, T stage and histological grade, indicating the vital part of CENPK in human cancer pathogenesis." (PMID 33904381, 2021). "We analyzed the association between mRNA expression of CENPK and clinical-pathological parameters of patients with LAC, including cancer stage, T stage, lymphatic metastasis, distant metastasis, sex, and age." (PMID 33478508, 2021). "Several pieces of evidence have suggested the relation of CENPK with carcinogenesis and cancer progression." (PMID 33478508, 2021). "The overexpression of CENPK promoted cell proliferation and migration that was correlated with a poor prognosis, and the expression downregulation of CENPK suppressed cell growth and inhibited cancer progression." (PMID 37938151, 2023). "Besides, tumorigenicity analysis revealed that CENPK knockdown markedly inhibited cancer development while overexpressed CENPK evidently promoted tumor growth in vivo." (PMID 33904381, 2021). "The role of centromere protein K (CENPK) in cancer is an emerging research hotspot." (PMID 33478508, 2021). "Previous studies have described the prognostic significance of CENPK for certain cancers." (PMID 33478508, 2021). "We also identified a few novel associations in lung tumours (LUAD), for instance CENPK has not previously been associated with this cancer type, even though the gene had already been associated to ovarian cancer." (PMID 28387377, 2017). "Besides, CENPK expression in LAC was related to cancer stage, T stage and distant metastasis." (PMID 33478508, 2021). "The human CD44/MYC-high cluster expressed CENPK and CENPN, which regulate the cell cycle and cell division in cancer." (PMID 35611554, 2022). "Thus, CENPK may be a potential target for cancer therapeutics in GC." (PMID 34382342, 2021).
tumor (14 papers, 2015 to 2024). "Our studies provide initial evidence of the role of CENPK exon-skipping variant in mCRPC tumor growth and Abiraterone resistance." (PMID 39404386, 2024). "We performed a pathway enrichment analysis of CENPK-related genes and identified some pathways; the results showed an association of CENPK over-expression with tumor progression and poor outcomes." (PMID 33478508, 2021). "The identified splice variant genes (CENPK, PKN1, KIAA1324, EMD, and TSC2) associated with response were mainly related to mitosis, PI3K–Akt cell survival/proliferation signaling, and tumor progression and metastasis." (PMID 39404386, 2024). "Mice with downregulated CENPK in HeLa and SiHa cells exhibited decreased tumor formation, fewer lung metastases, and slower growth rates than the corresponding controls." (PMID 35418160, 2022). "Multivariate analysis showed that CENPK expression levels and clinicopathological characteristics, such as age, histologic grade, tumour stage and distant metastasis in GC patients were independent prognostic factors for OS." (PMID 34382342, 2021). "In the present study, we identified overexpression of CENPK in LAC; in addition, high CENPK expression showed an association with tumor progression." (PMID 33478508, 2021). "To investigate the mechanism by which CENPK promotes tumour cell proliferation, we examined the effect of CENPK on the cell cycle using flow cytometry." (PMID 34382342, 2021). "Recently, several studies have investigated the biological activities of CENPK in tumor progression and metastasis." (PMID 33478508, 2021). "Knockdown and overexpression of CENPK showed consistent effect on DTC tumor growth and expression of Ki-67 invivo." (PMID 33904381, 2021). "Data from TCGA revealed overexpression of CENPK in LAC samples (n = 535) compared with the non-tumor samples (n = 59)." (PMID 33478508, 2021). "The expression of CENPK in MSI‐H was significantly higher than that in MSS/MSI‐L (p = 0.028), and the expression of CENPK in the pathological stage tumour depth T3‐T4 was observably higher than that in T1‐T2 (p = 0.0052)." (PMID 34382342, 2021). "We then analysed the expression levels of CENPK mRNA in xenograft tumours and found that CENPK mRNA levels were significantly lower in the shCENPK group than in the control group (p < 0.0001)." (PMID 34382342, 2021). "Several studies have found that CENPK is overexpressed in several tumor types and promotes tumor progression." (PMID 33658048, 2021). "Our findings indicate a potential role of CENPK in promoting tumor proliferation, invasion, and metastasis." (PMID 33478508, 2021). "Tumour xenograft studies further demonstrated the function of CENPK in accelerating GC growth in nude mice." (PMID 34382342, 2021). "It was demonstrated that cell lines transduced with CENPK shRNA lentivirus in in vivo experiments can produce smaller tumours due to CENPK silencing." (PMID 34382342, 2021). "Zinc finger CCCH-type containing 13 (ZC3H13) is a highly expressed oncogenic m6A writer that modulates centromere protein K (CENPK) and cytoskeleton-associated protein 2 (CKAP2) expression to promote malignant properties, tumour stemness and chemoresistance in CC patients (Refs 45, 46)." (PMID 39377535, 2024). "Further analysis showed that CENPK regulates the growth of tumor cells through YAP1." (PMID 37370088, 2023). "It is believed that CENPK may modulate the tumor-related signaling pathways to influence cell proliferation and promote the occurrence and development of LAC." (PMID 33478508, 2021). "Previous researches promoted several potential pathways by which CENPK may be involved in tumor proliferation, migration, and invasion." (PMID 33904381, 2021). "Overall, our results support the view that CENPK may be an essential pro-tumor molecule in DTC." (PMID 33904381, 2021). "Therefore, CENPK possibly plays a role of the tumor-promoting molecule within DTC." (PMID 33904381, 2021).
tumor (continued). "The increase of CENPK expression further activates the expression of YAP1, which leads to the activation of CRC tumor signal pathway." (PMID 37370088, 2023). "After 24 days, Ki-67 expression, tumor weight, and tumor volume decreased in shCENPK group relative to sh-CON group, while those in the CENPK group increased relative to the vector group." (PMID 33904381, 2021). "Interestingly, from these 17 significant pairs (adjusted p-value ≤ 0.05) several downregulated tumour-suppressor miRNAs (e.g., miR-let-7c, miR-139, miR-145 or miR-195) appeared to regulate oncogenic genes related to the cell cycle and DDR pathways (BUB1B, AURKA, BIRC5, CENPK, BRCA1 and CHEK1)." (PMID 28387377, 2017).
adenocarcinoma (2 papers, 2016 to 2021). A common cancer characterized by the presence of malignant glandular cells. "To choose the proper cell model for follow-up research, we compared the protein expression of CENPK in different cells, including HBE cell, adenocarcinoma cell lines (A549 and H1299) and NSCLC cell line (A427)." (PMID 33478508, 2021).
CENPK also shares sentences with these, for which no sentence is quoted: breast carcinoma (2 papers); thyroid cancer (2); leukemia (1); oligodendroglioma (1); ovary (1); papillary thyroid cancer (1); serous ovarian carcinoma (1); small cell lung carcinoma (1); tongue squamous cell carcinoma (1).